IL1B (interleukin 1 beta)
Diseases named in the same sentence as IL1B in open-access papers (continued):
Sharing a sentence is not in itself a finding about the gene and the disease.
Obesity (continued). "Concerning the slight increase in IL-1β in PCOS-like inguinal WAT, it could be concluded that mainly IL-6 contributed to the chronic inflammatory in WAT under obesity condition." (PMID 35436959, 2022). "Peripheral inflammation, mainly driven by IL-1β, TNF-α and IL-6, have been related to the disturbance of metabolic processes in individuals with schizophrenia (including insulin resistance, hepatic inflammation, and obesity)." (PMID 35625844, 2022). "IL-1β levels induced by [Ca2+]ex were significantly higher not only in MDM from patients with obesity compared to controls, but also in visceral versus subcutaneous AT." (PMID 35931812, 2022). "Furthermore, Tyzzerella was positively correlated with the majority of the obesity indicators, including body weight, liver weight, perirenal fat, mesenteric fat, TG, T-CHO, blood glucose, HOMA-IR, TNF-α, and IL-1β." (PMID 35548566, 2022). "Obesity results in the increased secretion not only of TNF but also of resistin, IL1β and IL6." (PMID 36233290, 2022). "In addition to NLRP3, experimental studies have demonstrated that caspase-1 is also involved in NAFLD/NASH, as it can process pro-IL-1β to its bioactive form, IL-1β, which has a key role in accelerating NAFLD development and inflammation induced by obesity." (PMID 35350750, 2022). "Markers of inflammation such as interleukin-1 beta (IL-1β), tumor necrosis alpha (TNF-α), monocyte chemoattractant protein-1 (MCP-1 or CCl-2), and interleukin 6 (IL-6), and markers related to obesity such as leptin and insulin were measured systemically in the blood." (PMID 36387539, 2022). "We show, that the [Ca2+]ex-induced IL-1β response of macrophages is increased in obesity compared to people who were not obese, and in visceral compared to subcutaneous AT." (PMID 35931812, 2022). "This can be the case for metabolic diseases, such as metabolic syndrome, obesity, and type 2 diabetes mellitus (T2DM), as well as some auto-inflammatory disorders, which may benefit from IL-1β blockers, or even NLRP3 inflammasome inhibitory therapies." (PMID 35111374, 2022). "In obesity, production of IL6 is stimulated by both IL-1β and TNFA81." (PMID 33820928, 2021). "In this work, we address the hypothesis that during obesity-induced IR, there is an increase in the NLRP3 inflammasome complex, IL-1β, and GSDMD protein content in the skeletal muscle." (PMID 34638553, 2021). "In animal models of obesity and insulin resistance it was shown that the inhibition of FABP4 protein in macrophages reduces inflammatory cytokines (MCP-1, IL-1β, IL-6 and TNFα) and the formation of atherosclerotic lesions and foam cells and improves insulin sensitivity." (PMID 34834808, 2021). "Luminex analysis showed that in the HFD-induced obesity mouse model, there was an obvious increase in serum proinflammation cytokines such as TNF-α, MCP-1, IL-12, IL-1β, IL-6, CCL3, CXCL16, and Resistin, which were further alleviated significantly in the CD226KO group." (PMID 34823548, 2021). "Inflammatory signals, like IL-1β, TNF-α, IL-6, and TLR ligands, have all been shown to impact the HSC pool during acute and chronic inflammation and, interestingly, are also all elevated during obesity." (PMID 33554957, 2021). "Indeed, circulating levels of several inflammatory cytokines (i.e., CRP, IL‐1β, IL‐6, IL‐8, MCP‐1, and TNFα) have been shown to be increased in obesity." (PMID 34110720, 2021). "The present study demonstrated that 12 weeks of synbiotic supplementation significantly reduced the physical parameters as well as the inflammation markers IL-6, IL-1β, TNF-α and other obesity markers including LPS, zonulin, 5-HIAA, and QA in Thai obese subjects." (PMID 34359450, 2021). "Pro-inflammatory cytokines such as TNF-α, IL-1β, and IFN-γ dose- and time-dependently suppress adiponectin secretion by adipocytes, which probably accounts for the decreased plasma levels during chronic inflammation in obesity." (PMID 34639186, 2021).
Obesity (continued). "It is known that (pre)adipocytes, a predominant cell type present in the adipose tissues, express and secrete a variety of adipokines (leptin, adiponectin, etc.)as well as inflammatory cytokines (TNF-α, IL-1β, IL-6, etc.)and enzymes (iNOS, COX-2, etc.), which confer obesity inflammation." (PMID 34063048, 2021). "Adipose tissue hyperplasia during obesity induces the secretion of adipocytokines such as leptin, interleukin-6 (IL-6), interleukin-1β (IL-1β), IL-10, TNF-α, monocyte chemo-attractant protein-1, and plasminogen activator inhibitor-1, which are responsible for obesity-related inflammation." (PMID 33946303, 2021). "The obesity-related asthma phenotype is also associated with the presence of increased interleukins levels, such as TNF-α and IL-1β in the lung, even in the absence of an antigenic challenge." (PMID 33418879, 2021). "Blood and tissue inflammatory cytokine levels including either TNF-α, IL-1b, IL-6, IL-10, or MIP-2a were also increased with obesity in 22 of 30 cases and may have contributed to inflammatory organ injury and worsened survival." (PMID 32211204, 2020). "The effect of burns and obesity on the expression of MCP-1, TNF-α and IL-1β protein." (PMID 33354433, 2020). "Recent studies suggest that diet-induced obesity alone may reprogram skeletal muscle to increase the production of inflammatory cytokines, including TNFα, MCP1, and IL-1β." (PMID 32316567, 2020). "In obesity, the MCP-1 secreted by both hypertrophic adipocytes and M1 macrophages has been reported to accelerate macrophage infiltration into the adipose tissue and increase adipose tissue-derived IL-6 and IL-1β levels." (PMID 32019160, 2020). "Other studies have also demonstrated that the development of obesity increases the secretions of various pro-inflammatory chemokines and cytokines from adipose tissues, such as tumor necrosis factor-alpha (TNF-α), interleukin-1beta (IL-1β), IL-6 and monocyte chemoattractant protein-1 (MCP-1)." (PMID 32143330, 2020). "Increases in IL-1β and TNFα, have been proposed to contribute to the innate AHR of obesity." (PMID 32326950, 2020). "Although obesity is considered a low-grade systemic inflammatory state, in the present study, we did not observe differences in us-CRP and in most of the cytokines analysed in blood serum (IL-6, TNF-α, IL-1β, IL-10, MCP-1 and leptin)." (PMID 33489104, 2020). "In addition, obesity leads to an increase in tumor infiltrating macrophages with activated NLRC4 inflammasome and increased IL-1β production in breast tumors." (PMID 33339340, 2020). "Taken together, our results, obtained from colonic tissues isolated from HFD mice and cultured EGCs, point to the concept that enteric glial alterations, occurring in the presence of obesity, sustain both bowel motor dysfunctions and enteric inflammation, through GDNF, SP, and IL-1β release." (PMID 32443525, 2020). "Factorial analysis showed that obesity and burn severity had no interactive effect on IL-1β expression." (PMID 33354433, 2020). "A long period of EGCG treatment reduced obesity development, and symptoms related to metabolic diseases and fatty liver through reduced lipid absorption and decreased inflammatory cytokines such as TNF-α, IL-1β, and IL-6." (PMID 32641048, 2020). "In research studies about obesity, acupuncture could regulate inflammatory cytokines, such as TNF-α, IL-6, and IL-1β and inflammatory cells, such as macrophages." (PMID 32595736, 2020). "In contrast, IL1B and NOS2 were significantly increased in islets from obese, compared to non-obese individuals, implying a more inflammatory macrophage phenotype in islets in obesity." (PMID 31787760, 2019). "In obesity, many proinflammatory immune cells, including M1 macrophages and Th1 cells, infiltrate and accumulate in muscle tissues, which secrete proinflammatory cytokines, such as TNF-α, IL-1β, and MCP1." (PMID 31582899, 2019).
Obesity (continued). "We observed that IL-1α, but not IL-1β serum levels were significantly influenced by EDs diagnosis, being essentially higher in AN patients or patients with obesity with or without BED than in HCs, while they were not influenced by BMI or depression." (PMID 31450770, 2019). "Moreover, in this obesity model, CARD9 deletion reduced IL-6 and IL-1β levels in plasma as well as pro-inflammatory cytokine secretion from isolated peritoneal cells." (PMID 30867470, 2019). "In a different recent study, significantly increased saliva levels of anti-inflammatory oxytocin and pro-inflammatory IL-1β were detected in the saliva of migraine patients treated before and after VNS treatment, while obesity was present in only 30% of the cohort." (PMID 31554241, 2019). "Obesity leads to the polarization of macrophages from the M2 to the M1 phenotype in fat tissues and aggravate inflammation in the fat tissue by increasing the proportion of M1 macrophages which secrete pro-inflammatory cytokines such as TNF-α and IL-1β." (PMID 31731817, 2019). "Alongside S100A8/A9, a number of endogenous TLR-4 ligands including gut-derived LPS, HMGB1, and modified LDL are elevated in the plasma and adipose tissue in obesity and may contribute to ATM priming to produce IL-1β." (PMID 31249530, 2019). "A meta-analysis of the influence of adipokine polymorphisms in adipokine genes (LEP, ADIPOQ, IL-1β, IL-6, and TNF-α) in obesity susceptibility showed that there was not association with the risk of obesity and LEP variants in adults." (PMID 31354816, 2019). "For example, obesity induces an increase in tumor-infiltrating MDSCs with activated NLRC4 inflammasome, leading to IL-1β production, which drives tumor progression through adipocyte-mediated vascular endothelial growth factor (VEGF) A expression and angiogenesis." (PMID 31182982, 2019). "Obesity induced by high-fat diet (HFD) is accompanied by not only the body weight increase, adipose deposition in liver and other organs, but also oxidative stress and inflammation increase, such as IL-1β, TNF-α and iNOS." (PMID 30736329, 2019). "A mouse metabolic study comparing the effects of inflammation from HFD with diet-induced obesity and from DSS exposure showed DSS exposure increased cytokines IL-1β and IL-12p40 in the liver, mesenteric fat, and subcutaneous fat, without effects on glucose or insulin." (PMID 31179345, 2019). "In the development of obesity in mice induced by a high-fat diet, pretreatment with casein hydrolysate showed that NLRP3 inflammasome-mediated IL-1β secretion in adipose tissue could be attenuated." (PMID 31174550, 2019). "We hypothesize that obesity increases AHR via the IL-1β mechanism, which can be prevented by caloric restriction and IL-1β blockade." (PMID 30670753, 2019). "At this relatively early stage of obesity, however, there was no detectable increase in protein concentrations of inflammatory cytokines in the extracellular fluid of BM including IL-1b, interleukin 6 (IL-6) or tumor necrosis factor (TNF)." (PMID 29453396, 2018). "Obesity and dyslipidemia induce abnormal growth of adipose tissue, contributing to the overproduction of inflammatory mediators [particularly TNF-α, IL-6, and interleukin-1 beta (IL-1β)] and activation of nuclear factor-kappa B (NF-κB)." (PMID 28725195, 2017). "Specifically, anti-inflammatory cytokines interleukin- (IL-) 13, IL-4, and IL-10 stimulate the alternatively activated ATMs (M2) in lean persons, while obesity induces a shift to the classically activated ATMs (M1) due to stimulation by proinflammatory cytokines TNF-α, IL-1β, and IL-6." (PMID 28293435, 2017). "Moreover, in obese asthma mice, IL-1β mRNA and NLRP3 mRNA expression were significantly increased compared with the asthma and obesity groups (P<0.05)." (PMID 29160418, 2017).
Obesity (continued). "In experimental models, it has been reported that obesity and excessive nutrition alters the inflammatory response, with increasing concentrations in TNF- α, IL1b, and IL-6, among others, resulting in the development of insulin resistance and excessive fetal growth." (PMID 28749954, 2017). "In summary, the present study showed that obesity created a low-grade chronic inflammatory microenvironment in the mammary tissue of women, as indicated by the elevations of several inflammatory cytokines, including TNF-α, IL-6, and IL-1β." (PMID 28402277, 2017). "Obesity and adipogenesis could increase production and secretion of proinflammatory cytokines such as TNF‐α, IL‐1β, and IL‐6 from macrophages into adipose tissues." (PMID 28572933, 2017). "In these cases, the antioxidant action of GTCs is likely involved in their anti-obesity mechanism owing to the fact that ROS stimulate nuclear factor-κB, which in turn promotes the expression of proinflammatory cytokines, such as TNF-α and IL-1β." (PMID 27689985, 2016). "GTCs may exert anti-obesity effects through suppression of TNF-α and IL-1β expression, since these inflammatory cytokines are known to upregulate the expression of SREBP-1 and stimulate the maturation of the SREBP-1 protein." (PMID 27689985, 2016). "Elevated plasma levels of inflammatory cytokines (including interleukin (IL)-1β, tumor necrosis factor (TNF)-α, IL-6 and C-reactive protein) have been reported in obese patients and different animal models of obesity." (PMID 26190966, 2015). "Given the pivotal role of IL‐1β and TNFα in nonpregnancy‐related obesity, we examined secretion and gene expression in gonadal fat depots." (PMID 25096554, 2014). "This is consistent with the previous report that the release of interleukins including IL-1β by human adipose tissue is enhanced in obesity and is primarily due to the nonfat cells." (PMID 24918199, 2014). "IL-1β and IFN-γ are two other cytokines that increase with obesity." (PMID 25324698, 2014). "Collectively these results demonstrate that diet-induced obesity in the absence of IL-1β alters adipose tissue in a manner less detrimental to adipose-liver crosstalk." (PMID 23341960, 2013). "Yet, in WT conditions when IL-1β is present, it does not seem to directly mediate the disturbed fat-liver crosstalk induced by obesity." (PMID 23341960, 2013). "Consistent with previous reports of obesity-prone C57BL/6 mice responding to a high-fat diet with the induction of a proinflammatory response, this work demonstrates increased spleen production potential of IFNγ, IL1β, and IL-17." (PMID 20877574, 2010). "However, the mRNA levels of individual Tnfα, Il1b, or Mcp-1 are differentially expressed among CD9+CD11c−, CD9−CD11c+, and CD9+CD11c+ ATMs, suggesting functional heterogeneity even among proinflammatory ATMs during obesity." (PMID 39071288, 2025). "The increased expression levels of Il1b in the ileum and colon of rats under a HFD are in line with the results obtained with the human samples, suggesting a pro-inflammatory environment in the colon from rats with obesity that may favor CC development." (PMID 39305371, 2025). "In addition, HFD‐NLRP3−/− mice displayed a reduction in active caspase‐1 expression as well as in circulating and colonic IL‐1β levels, thus confirming previous evidence describing the involvement of NLRP3 inflammasome in the pathophysiology of obesity and related inflammation." (PMID 39287080, 2025). "However, the mRNA levels of individual Tnfa, Il1b, or Ccl2 are differentially expressed among CD9+CD11c-, CD9-CD11c+, and CD9+CD11c+ ATMs, suggesting functional heterogeneity even among proinflammatory ATMs during obesity." (PMID 40244655, 2025). "The inflammation hypothesis suggests that obesity is a chronic inflammatory state, and inflammatory factors such as TNF-α, interleukin-1β (IL-1β), and IL-6 can decrease tissue sensitivity to insulin and lead to pathological changes in pancreatic β-cell function." (PMID 40842495, 2025).
Obesity (continued). "Accordingly, lack of endogenous IL‐1β signaling in mice during refeeding and obesity could reduce the concentration of insulin in plasma with consequent normalization of glucose metabolism and body weight gain." (PMID 39287080, 2025). "The model exhibits pronounced cardiometabolic dysfunction, including obesity, insulin resistance, dyslipidemia, QTc prolongation, reduced QRS amplitude, and elevated markers of myocardial injury (Troponin T, CK-MB) and systemic inflammation (IL-6, IL-1β, TNF-α) (p < 0.05)." (PMID 41309777, 2025). "For example, bioinformatic comparison of transcriptomes in polycystic ovary syndrome (PCOS), obesity, and T2DM identified jointly dysregulated genes (including IGF2R, the insulin-like growth factor 2 receptor) and network “hub” proteins such as STAT3, IL1B, and PF4." (PMID 41303351, 2025). "Obesity resulted in a marked increase in the expression of cyclooxygenase-2 (COX-2) and IL-6 in the adipose tissue of HFD animals, with concurrent moderate increases in TNF-α, IL-17A, and IL-18, while IL-1β changes were minor and inducible nitric oxide synthase (iNOS) expression was reduced." (PMID 38672413, 2024). "Higher levels of IL-1β (A, p < 0.0001), IL-6 (B, p < 0.0001), IP-10 (E, p < 0.001), GM-CSF (F, p < 0.0001), TNF-α (G, p < 0.0001), and IFN-γ (H, p < 0.0001), and lower IL-10 levels (I, p < 0.05) were found in the volunteers with obesity compared with the NW group." (PMID 39125408, 2024). "Moreover, network construction produced similar results: Rumonococcus, Lachnospiraceae_NK4A136-group, Prevotellaceae_NK3B31_group, and Clostridium_sensu_stricto_1 were involved in the accumulation of IL-1β, TNF-α, MG,AGEs, TG, AgRP, and SOCS3 for the development of obesity." (PMID 38659208, 2024). "Thus, the decrease in NA concentration explains the increase in the IL-1β and the absence of significant modifications in the concentration of IL-6 in the present model of obesity." (PMID 39064652, 2024). "We did not detect any effect of obesity or diet on liver IL-10 or IL-1β expression." (PMID 38075211, 2023). "Besides, PQQ also could protect hepatocyte from lipotoxicity and inflammation followed obesity via down-regulating the level of pro-inflammatory cytokines (NLRP3, IL-6, TNF and IL-1β)." (PMID 37935689, 2023). "During obesity, the energy excess leads to adipose expansion generating hypertrophic adipocytes that produce a wide variety of proinflammatory molecules, such as monocyte chemoattractant protein-1 (MCP-1), TNF-α, IL-1β, and IL-6 that activate and attract the immune system cells." (PMID 37139092, 2023). "Gouranton and his co-workers demonstrated in their study that lycopene had a moderating effect on the formation of IL-1β, IL-6 and TNF-α in adipose tissue and eventually might prevent or reduce the incidence of obesity-related diseases including insulin resistance." (PMID 36826001, 2023). "Increased IL-1β levels are attributed to NF-κB activation and NOD-like receptor family, pyrin domain containing 3 (NLRP3) activity, which in turn could be stimulated in obesity by several factor such as FA, cholesterol, ROS and hyperglycemia." (PMID 37266440, 2023). "While alone this endogenous signal(s) was insufficient to induce WAT IL-1β-secretion at baseline to detectable levels, its effects together with the mass of WAT cannot be ignored when evaluating the physiological effects of LDL, ATP and LPS particularly with obesity and IR." (PMID 37914804, 2023). "Therefore, obesity or T2DM models, effective inhibition of NLRP3 inflammasome activation reduces the inflammatory response of β cells, thereby improving insulin sensitivity by inhibiting the production of IL-1β." (PMID 36993972, 2023). "A large body of evidence suggests that inflammatory cytokines such as TNF-α, IL-1β, and IL-6 not only induce systemic insulin resistance but also affect lipid metabolism, whereas the presence of IL-10 effectively improves insulin sensitivity and HFD-induced obesity." (PMID 38162665, 2023).